MIR4325 (microRNA 4325)
Synonyms: hsa-mir-4325
Gene: MicroRNA gene on chromosome 20 (57,321,502 to 57,321,591, reverse strand). Ensembl gene ENSG00000266666.
Homologues: Orthologues: chimpanzee MIR4325 (100% identical).
Diseases named in the same sentence as MIR4325 in open-access papers:
MIR4325 is named in the same sentence as 1 disease in open-access papers, as found by Europe PMC text mining. Sharing a sentence is not in itself a finding about the gene and the disease.
MIR4325 shares sentences with these, for which no sentence is quoted: cancer (1 paper).